AP3D1 (adaptor related protein complex 3 subunit delta 1)
Description:
Part of the AP-3 complex, an adaptor-related complex which is not clathrin-associated. The complex is associated with the Golgi region as well as more peripheral structures. It facilitates the budding of vesicles from the Golgi membrane and may be directly involved in trafficking to lysosomes. Involved in process of CD8+ T-cell and NK cell degranulation. In concert with the BLOC-1 complex, AP-3 is required to target cargos into vesicles assembled at cell bodies for delivery into neurites and nerve terminals (By similarity).
Synonyms: ADTD; HPS10; hBLVR
Tractability: Small molecule: a structure with a bound ligand is known. Antibody: UniProt places it where antibodies can reach, with medium confidence. PROTAC: ubiquitination databases record sites on it; its protein half-life has been measured.
Gene: Protein-coding gene on chromosome 19 (2,100,982 to 2,164,468, reverse strand). Ensembl gene ENSG00000065000.
Subcellular location: Cytoplasm; Golgi apparatus membrane
Subcellular location (Human Protein Atlas): Cytosol
Gene Ontology:
Molecular function: protein binding; AP-3 adaptor complex binding
Biological process: endosome to melanosome transport; protein localization to membrane; zinc ion import into lysosome; anterograde axonal transport; anterograde synaptic vesicle transport; clathrin-coated vesicle cargo loading, AP-3-mediated; Golgi to vacuole transport; intracellular protein transport; melanosome assembly; melanosome organization; neurotransmitter receptor transport, postsynaptic endosome to lysosome; platelet dense granule organization; protein targeting to vacuole; synaptic vesicle budding from endosome; synaptic vesicle coating; synaptic vesicle membrane organization; synaptic vesicle recycling; vesicle-mediated transport; intercellular transport; lysosomal transport; otolith development; protein transport; vesicle coating; vesicle organization
Cellular component: endosome membrane; lysosomal membrane; membrane; AP-3 adaptor complex; early endosome; Golgi apparatus; presynaptic endosome; terminal bouton; axon; axon cytoplasm; cytoplasm; glutamatergic synapse; Golgi membrane; membrane coat; microvesicle; postsynapse; presynapse
Genetic constraint (gnomAD): Loss-of-function variants: 46 observed, 132.81 expected, observed/expected ratio (o/e) 0.35, 90% interval 0.27 to 0.44. The upper end of that interval is the gene's LOEUF score, 0.44, which puts it in group 1 of 6, group 1 being the genes least tolerant of losing a copy. Missense variants: 1,366 observed, 1,569.5 expected, observed/expected ratio (o/e) 0.87, 90% interval 0.83 to 0.91. Synonymous variants: 736 observed, 641.14 expected, observed/expected ratio (o/e) 1.15, 90% interval 1.08 to 1.22.
Gene-disease validity (ClinGen):
ClinGen rates the evidence that AP3D1 causes each of these diseases.
Hermansky-Pudlak syndrome 10 (autosomal recessive): Moderate. Any Hermansky-Pudlak syndrome in which the cause of the disease is a mutation in the AP3D1 gene.
Homologues: Orthologues: chimpanzee AP3D1 (99% identical), macaque AP3D1 (98% identical), mouse Ap3d1 (89% identical), rat Ap3d1 (88% identical), dog AP3D1 (88% identical), pig AP3D1 (87% identical), guinea pig AP3D1 (84% identical), tropical clawed frog ap3d1 (81% identical), zebrafish ap3d1 (77% identical), Caenorhabditis elegans apd-3 (48% identical), Drosophila melanogaster g (47% identical).
Diseases named in the same sentence as AP3D1 in open-access papers:
AP3D1 is named in the same sentence as 37 diseases in open-access papers, as found by Europe PMC text mining. Sharing a sentence is not in itself a finding about the gene and the disease. The quoted sentences say what the papers report.
Immunodeficiency (4 papers, 2021 to 2023). Failure of the immune system to protect the body adequately from infection, due to the absence or insufficiency of some component process or substance. "Consistent with the report on one patient with an AGAP1 variant, the patient with the AP3D1 variant had immunodeficiency and died of septic pneumonia at the age of 3.5 years." (PMID 37470098, 2023). "AP3D1 mutation is associated with immunodeficiency and seizures and defines a new type of Hermansky-Pudlak syndrome." (PMID 34874227, 2021). "Consistent with this, mutations in the AP3D1 gene cause serve neurological disorders (e.g., Hermansky−Pudlak syndrome), including immunodeficiency, as well as albinism, and can also lead to altered retinal cell differentiation, particularly of amacrine cells, in mice." (PMID 34440217, 2021). "Loss-of-function variants in AP3D1 have been linked to Hermansky–Pudlak syndrome (HPS) 10, a severe multisystem disorder characterized by oculocutaneous albinism, immunodeficiency, neurodevelopmental delay, hearing loss (HL), and neurological abnormalities, fatal in early childhood." (PMID 36445457, 2023).
albinism (3 papers, 2021 to 2023). A congenital disorder characterized by partial or complete absence of melanin pigment in the eyes, hair, or skin. "Pathogenic variants in both BLOC1 or AP‐3 complex (AP3B1 and AP3D1) are associated with Hermansky‐Pudlak syndrome, in which neurodevelopmental and non‐neuronal phenotypes (albinism, PID) result from lysosomal defects." (PMID 35880319, 2022). "Our results indicate that a missense variant in AP3D1 causes human syndromic HL with HPS10-like symptoms in the absence of albinism and bleeding diathesis." (PMID 36445457, 2023).
colorectal cancer (2 papers, 2021 to 2022). A primary or metastatic malignant neoplasm that affects the colon or rectum. "IFNGR1 in colorectal cancer cells can be palmitoylated, which allows its interaction with AP3D1, a lysosome sorting adapter, and facilitates IFNGR1 lysosomal sorting and degradation." (PMID 34385592, 2022). "Given that IFNGR1 palmitoylation is essential for its interaction with AP3D1 and subsequent IFNGR1 lysosomal sorting and degradation in colon cancer, suppression of IFNGR1 palmitoylation can restore cancer IFNγ signaling integrity and sensitize colorectal cancer cells to immunotherapy." (PMID 34385592, 2022).
Hermansky-Pudlak syndrome (2 papers, 2021 to 2025). Hermansky-Pudlak syndrome (HSP) is a multi-system disorder characterized by oculocutaneous albinism, bleeding diathesis and, in some cases, neutropenia, pulmonary fibrosis, or granulomatous colitis. "Genetic analysis revealed AP3D1 gene mutation suggestive of Hermansky-Pudlak Syndrome (HPS) type 10." (PMID 41025021, 2025).
Arterial stenosis (1 paper, 2021). Narrowing or constriction of the inner surface (lumen) of an artery. "Consistently, Spearman correlation analysis revealed a significant association between s-AP3D1-Ab levels and max IMT (P < 0.001), which reflects arterial stenosis, namely, atherosclerosis." (PMID 34188129, 2021).
atherosclerosis (1 paper, 2021). A disease characterized by the build-up of fatty material and calcium deposition in the arterial wall resulting in partial or complete occlusion of the arterial lumen. "Correlation analysis showed that the anti-AP3D1 antibody levels were highly associated with maximum intima-media thickness, which indicates that this marker reflected the development of atherosclerosis." (PMID 34188129, 2021). "Through the initial SEREX screening, AP3D1 was identified as an antigen recognized by serum IgG in patients with atherosclerosis." (PMID 34188129, 2021). "In this study, using the SEREX method screening, adaptor-related protein complex 3 subunit delta 1 (AP3D1) was identified as a target antigen recognized by serum IgG antibodies in the sera of patients with atherosclerosis." (PMID 34188129, 2021). "s-AP3D1-Ab marker was closely associated with max IMT, an index of atherosclerosis, which then leads to the onset of AIS and AMI." (PMID 34188129, 2021). "AP3D1 can possibly mediate angiotensin II-induced HT and atherosclerosis." (PMID 34188129, 2021). "Therefore, s-AP3D1-Ab marker may discriminate a certain type, if not all, of atherosclerosis caused by HT or DM, leading to the development of AIS and CVD." (PMID 34188129, 2021). "Lastly, physiological testing, such as baPWV, or coronary artery calcification, was not performed to evaluate atherosclerosis in subjects subjected to the s-AP3D1-Ab analysis." (PMID 34188129, 2021).
cervical cancer (1 paper, 2019). A primary or metastatic malignant neoplasm involving the cervix. "In addition, AP3D1 was reported to be involved in fusions in cervical cancer, lung cancer and colon cancer in the FusionCancer database, indicating that AP3D1 may be widely involved in fusions in human cancer." (PMID 30903738, 2019).
melanoma (1 paper, 2023). A malignant, usually aggressive tumor composed of atypical, neoplastic melanocytes. "Four additional melanoma somatic mutation hotspots (> 3 mutations) were present in the assayed regions: TERT, encoding one subunit of telomerase and known to be frequently activated by somatic promoter mutations in cancer, and three ETS-related sites (RPL13A, AP3D1 and EGR1)." (PMID 37169761, 2023).
primary ovarian insufficiency (1 paper, 2023). "Since all previously reported HPS10 cases were pediatric, it is unknown whether the observed primary ovarian insufficiency recapitulates the subfertility in Ap3d1-deficient mice." (PMID 36445457, 2023).
cancer (4 papers, 2019 to 2022). A tumor composed of atypical neoplastic, often pleomorphic cells that invade other tissues. "Atherosclerotic AIS and AMI and cancer have been identified as the leading causes of death; thus, the s-AP3D1-Ab marker would be highly useful to reduce its mortality." (PMID 34188129, 2021). "In addition, aberrant AP3D1 expression is associated with high risks for several cancers, heart attack and may be involved in chronic obstructive pulmonary disease through its binding to TGF bta2." (PMID 34565296, 2021). "AP3D1 has a positive effect in cancer, as it inhibits chemotherapy resistance in colorectal cells by maintaining signal integrity in tumor cells by preventing IFNGR1 lysosomal sorting." (PMID 34565296, 2021). "Based on the results, s-AP3D1-Abs levels were elevated in cancer patients." (PMID 34188129, 2021). "Genes containing AS events associated with overall survival are known components of cancer-related pathways, including regulation of transcription (E2F4, ZNF730, GPBP1, POLR2J, SP2, and CIART), cell cycle (E2F4 and GTSE1), or cell-cell adhesion (CEACAM1, MMP14, EPS8L2, AP3D1, AFDN, and PAK4)." (PMID 35044822, 2022). "Additionally, AP3D1 and all AP3 subunits are downregulated in cervical carcinoma, which suggests that AP3 might play a role in the cell-inherent anti-cancer pathway." (PMID 34565296, 2021). "Consequently, the s-AP3D1-Ab levels do not directly reflect DM, but are associated with DM-induced atherosclerotic disorders, which are also related to CKD and cancer." (PMID 34188129, 2021).
infection (2 papers, 2008 to 2018). The state of being infected such as from the introduction of a foreign agent such as serum, vaccine, antigenic substance or organism. "MHC class I receptors such as Cd1d1, B2m and Ap3d1 were also upregulated at 96 hr post infection." (PMID 18558011, 2008). "Studies in silico (like that described in this article) are necessary as a basis for initiating experimental studies verifying gp51 interaction with AP3D1, complementing existing information about BLV’s cellular receptor to achieve infection." (PMID 29928016, 2018).
tumor (2 papers, 2024 to 2025). "Commonly mutated genes, such as AP3D1, demonstrated a pronounced disparity, with a significantly greater percentage observed in primary tumours (38% vs. 8% in metastatic stage)." (PMID 39223638, 2024).
AP3D1 also shares sentences with these, for which no sentence is quoted: epilepsy (2 papers); neurologic disorders (2); oculocutaneous albinism (2); cardiovascular disease (1); chronic kidney disease (1); colon cancer (1); coronary artery (1); diabetes mellitus (1); dyslipidemia (1); Dystonia (1); esophageal squamous cell carcinoma (1); generalized epilepsy (1); Global developmental delay (1); hearing loss (1); Hypertension (1); leiomyoma (1); lung carcinoma (1); microcephaly (1); Neurodevelopmental delay (1); neutropenia (1); osteoarthritis (1); ovarian insufficiency (1); rheumatoid arthritis (1); transient ischemic attack (1); viral infection (1).